CRP (C-reactive protein)
Diseases named in the same sentence as CRP in open-access papers (continued):
Sharing a sentence is not in itself a finding about the gene and the disease.
rosacea (6 papers, 2021 to 2026). A chronic erythematous skin disorder that affects the face. "Hallmark indicators of inflammation, ESR and CRP were significantly higher in patients with rosacea." (PMID 37277425, 2023). "Monocyte and platelet count, MPV, SII index, ESR and CRP were statistically significantly higher in patients with rosacea than in the control group (p = 0.040, p = 0.006, p = 0.022, p = 0.026, p = 0.006, p < 0.001, respectively)." (PMID 37277425, 2023). "A study found slightly normal CRP levels in rosacea cases (>0.8 mg/L), and a meta-analysis revealed a significant association between rosacea and CRP." (PMID 37873776, 2023). "Monocyte and platelet count, SII index, ESR and CRP were significantly higher in patients with rosacea than in the control group." (PMID 37277425, 2023). "However, the levels of CRP, anti-microsomal antibody (anti-M), and prolactin were increased in rosacea patients." (PMID 34275693, 2021). "In patients with rosacea, the median monocyte was 0.53 (IQR:0.18) 109/L, platelet was 276 (IQR:91) 109/L, MPV was 10.5 (IQR:1.2) fl, ESR was 8 (IQR:10.5) mm/hour, CRP was 2.22 (IQR:4.34) mg/dl, and SII index was 517.20 (IQR:417.05) 109/L." (PMID 37277425, 2023). "Ocular rosacea patients with low LDL-cholesterol and high CRP levels could be identified and randomised to receive a statin in a similar fashion to observe for the reduction in both MGD and cardiovascular risk." (PMID 37512518, 2023). "When all the results are interpreted together, it can be concluded that all CBC parameters do not seem to increase in rosacea, but the SII index calculated by a formula (NLR x platelet) from these parameters seems to better reflect the inflammatory state indicated by ESR and CRP." (PMID 37277425, 2023).
skin ulceration (6 papers, 2021 to 2025). "Five variables—C-reactive protein level, elevated scrotal skin temperature, nodular lesion, chronic infection, and scrotal skin ulceration—were significant and used to construct the nomogram." (PMID 38956255, 2024). "Anti-melanoma differentiation-associated gene 5 (MDA5) antibody, lymphocytes in peripheral blood, C-reactive protein (CRP), skin ulceration, and ferritin were reported as predictive factors for disease onset and poor prognosis of RP-ILD." (PMID 34646845, 2021). "In univariate logistic regression analysis, age (odds ratio (OR) 1.18; 95% confidence interval (CI), 1.00−1.39; p = 0.049), skin ulcer or fistula (OR 11.69; 95% CI, 1.30−105.03; p = 0.028) and serum CRP level (OR 1.87; 95% CI, 1.14−3.08; p = 0.013) were factors associated with recurrence." (PMID 34066203, 2021). "Lesion size, percentage of multiple lesions, percentage of skin ulcer or fistula, CRP, and time to resolution were significantly different between the IGM patients with mild, moderate, and severe disease (p < 0.001, p < 0.001, p = 0.008, p < 0.001, p = 0.002, respectively)." (PMID 34066203, 2021).
staphylococcal infection (6 papers, 2010 to 2025). An infection caused by Staphylococcus. "However, it detected 64.3% and 58.3% of targeted staphylococcal infections associated with normal CRP and ESR values, respectively." (PMID 26865683, 2016). "However, the immunoassay detected around 60% of targeted staphylococcal infections associated with a normal ESR or CRP, demonstrating its ability to identify infection in the absence of systemic inflammation and to identifying patients otherwise overlooked by most diagnostic algorithms." (PMID 26865683, 2016). "Moderate TEAEs were abdominal pain, nausea, hypogammaglobulinemia, staphylococcal infection, increased C-reactive protein, decreased oxygen saturation level, insomnia, and nail bed inflammation (each reported in one participant)." (PMID 36441357, 2023). "It was positive in 64.3% and 58.3% of targeted staphylococcal infections associated with normal levels of CRP or ESR, respectively, and was also positive in one of the two S. agalactiae infections with a normal CRP." (PMID 26865683, 2016). "One of the interesting aspects of our results is that CRP values seem to be higher in K. kingae infections around the hip and could mimic Staphylococcal infections, even if K. kingae has historically been known as a weak pathogen presenting with mild clinical symptoms and biological abnormalities." (PMID 40828529, 2025). "Since IL-6 is pivotal for CRP induction, these results indicated that anti-IL-6 autoantibodies contributed to the lack of CRP response in this patient during staphylococcal infections." (PMID 21079687, 2010).
status epilepticus (6 papers, 2015 to 2024). Status epilepticus is defined as a continuous seizure lasting more than 30 min, or two or more seizures without full recovery of consciousness between any of them. "Interestingly, abnormal CRP in adults with status epilepticus has been shown to be independently associated with seizure refractoriness." (PMID 36645080, 2023). "CRP plasma levels seemed to be, however, slightly increased in patients with status epilepticus when compared with control." (PMID 34572093, 2021). "Therefore, we cannot exclude a higher CRP activity in dogs with status epilepticus, similar to that of dogs with SE." (PMID 39330787, 2024). "Previous research studies suggest that status epilepticus might increase the CRP’s concentration as a result of seizure-induced neuroinflammation regardless of etiology." (PMID 39330787, 2024). "Furthermore, the dog with cervical pain only was documented to have intracellular bacteria on CSF, a markedly elevated CRP and progressed rapidly to status epilepticus within 12 hours of presentation." (PMID 37325339, 2023). "Acute-phase proteins, such as procalcitonin (PCT), C-reactive protein (CRP) and albumin, may relate with course and outcome in status epilepticus (SE), as seizures bring about inflammation, changes of cytokine levels and blood–brain barrier breakdown." (PMID 26450065, 2015).
Streptococcus pneumonia (6 papers, 2013 to 2025). "In particular, on stearylamine-containing liposomes and on Types 6 and R36a Streptococcal pneumonia surfaces, CRP decreased serum C3-activation implicating CRP as a regulatory protein that can limit the extent of inflammatory damage initiated by C activation." (PMID 37781355, 2023). "CRP is an acute-phase protein that reacts with the C-polysaccharide of Streptococcus pneumonia." (PMID 41302955, 2025). "C-reactive protein (CRP), named for its capacity to precipitate the somatic C-polysaccharide of Streptococcus pneumonia, is a sensitive systemic marker of inflammation and tissue damage." (PMID 39408337, 2024).
Tachycardia (6 papers, 2020 to 2024). A rapid heartrate that exceeds the range of the normal resting heartrate for age. "Tachycardia, and raised CRP were also associated with prolonged DVS but presence or absence of symptoms was not." (PMID 34570805, 2021). "Tachycardia was more common in group 1 (P = .002), and group 3 had the highest C-reactive protein levels (P = .01)." (PMID 38813262, 2024). "The patient had normal blood pressure, blood oxygen saturation, sinus tachycardia, fever, crackles over the left lower lobe, novum incomplete right bundle branch block with Q waves and minor ST alterations, elevated C-reactive protein, high-sensitivity troponin-T, and d-dimer levels." (PMID 33962562, 2021).
thromboses (6 papers, 2020 to 2025). "Inflammatory markers, such as C-reactive protein (CRP), interleukin-6 (IL-6), and fibrinogen, have been widely studied in various diseases, including cancer and thrombotic disorders." (PMID 41169874, 2025). "Although the mean CRP level was higher in patients testing positive for LA by DRVVT (14.4 vs 7.5 mg/dL; P < .01), patients with thromboses did not have significantly higher CRP levels than those with no thromboses." (PMID 32785632, 2020).
thyroid autoimmunity (6 papers, 2018 to 2025). "Under the primary IVW analysis method, gPTSD was significantly positively associated with risk of autoimmune thyroid disease (beta = 0.150, SE = 0.018, p = 0.0001) and CRP (beta = 0.090, SE = 0.018, p = 4.3 × 10−7) after Bonferroni correction." (PMID 38561342, 2024). "Our analyses supported causal effects of PTSD on autoimmune thyroid disease (beta = 0.11, 95% CI = [0.07–0.14]; causal versus sharing model p = 2.6 × 10−3) and CRP (beta = 0.05, 95% CI = [0.04–0.07]; causal versus sharing model p = 8.5 × 10−8)." (PMID 38561342, 2024). "PTSD had putative causal effects on autoimmune thyroid disease (p = 0.00009) and C-reactive protein (CRP) (p = 4.3 × 10−7)." (PMID 38561342, 2024). "Interestingly, CRP level is also an independent risk factor for cardiovascular/metabolic and autoimmune disorders including autoimmune thyroiditis, a prominent comorbidity of BD." (PMID 29352395, 2018). "This may explain why we observed that the 3′-UTR CRP rs1130864 A minor allele carrier state is associated with autoimmune thyroiditis stringently in female patients." (PMID 29352395, 2018). "The gPTSD associations with autoimmune thyroid disease (N SNP instruments = 52, IVW beta = 0.122, SE = 0.037, p = 0.001) and CRP (N SNP instruments = 40, IVW beta = 0.084, SE = 0.015, p = 1 × 10−7) remained significant." (PMID 38561342, 2024). "The IVW effect estimates of PTSD on autoimmune thyroid disease (N = 38 instruments, beta = 0.11, SE = 0.04, p = 0.01) and CRP (N = 38 instruments; beta = 0.069, SE = 0.02, p = 0.001) were comparable in magnitude to the original estimates." (PMID 38561342, 2024). "This relationship is consistent with the well-known link between autoimmune thyroid diseases and CRP levels." (PMID 36810529, 2023). "Notably, this phenotype is also associated with increased levels of thyroid autoimmunity markers, such as thyroid autoimmunity (TPO antibodies) and the inflammatory markers CRP and IL-6." (PMID 39749338, 2024).
toxoplasmosis (6 papers, 2014 to 2021). A parasitic disease contracted by the ingestion or fetal transmission of toxoplasma gondii. "The maternal white blood cell count and serum C-reactive protein (CRP) were all normal and the screenings for TORCH (toxoplasmosis, rubella, cytomegalovirus, and Herpes simplex virus) serology were negative." (PMID 33845786, 2021). "Patients with toxoplasmosis exhibited normal ESR values in 9/11, 82%, and all had CRP values within the normal limits." (PMID 30411142, 2019). "Compared with controls, increased risk of SSD among offspring was indexed also by markers of inflammation, including elevated maternal interleukin-8 levels and C-reactive protein, but not maternal antibodies to toxoplasmosis." (PMID 26302744, 2015).
tularemia (6 papers, 2023 to 2025). Tularemia is an infection caused by the bacterium Francisella tularensis. "Consistent with human tularemia, all animals experienced decreases in lymphocyte counts and increases in neutrophil counts and CRP prior to treatment." (PMID 41251370, 2025). "C-reactive protein levels were lower in the tularemia group (19.3 ± 18.2 vs. 24.1 ± 28.1; p = 0.027)." (PMID 41150366, 2025). "Alanine aminotransaminase (p = 0.019) and C-reactive protein levels (p = 0.027) were significantly lower in the tularemia group." (PMID 41150366, 2025). "C-reactive protein (CRP), a serum biomarker of inflammation, increased markedly from pre-challenge to the development of tularemia for all study animals, with a mean increase of ≥11-fold at the time of treatment start." (PMID 37097147, 2023). "Consistent with the inflammatory pathophysiology of tularemia, the inflammatory marker CRP and the percentage of neutrophils were also elevated in all study animals early in the disease process." (PMID 37097147, 2023). "Similarly, C-reactive protein levels were found to be significantly lower in the tularemia group." (PMID 41150366, 2025). "Similarly, it has been reported in the literature that laboratory findings in cases of tularemia are often nonspecific, with mild-to-moderate increases in inflammatory markers such as CRP and sedimentation rate being observable." (PMID 41150366, 2025).
Urea (6 papers, 2017 to 2025). "As a group they had seen a worsening in their prognosis associated with Urea and CRP, but less change in respiratory rate, and a generally improved profile for oxygen saturation (which is likely partly due to receiving oxygen in hospital)." (PMID 36223373, 2022). "Urea, which commonly increases in children with dehydration, and CRP correlated with both severity scores." (PMID 39941614, 2025). "The findings in our study of increased ESR, CRP and Urea are all in lines with the work of teams led by Zeng, Ibnouf, Abo-Haded, and Yarijani." (PMID 37893025, 2023).
vivax malaria (6 papers, 2011 to 2020). "The SNPs were assessed regarding association with systemic levels of TNF, IL-6, CXCL10, and CRP, which have been associated with vivax malaria manifestations." (PMID 25038626, 2014). "IFN-γ/IL-10 ratio and CRP values marked the immune biosignature of vivax malaria patients, and could distinguish subjects with elevated creatinine levels who did not survive from those who did." (PMID 29596409, 2018). "When compared to symptomatic vivax malaria patients, coinfected individuals presented elevated levels of IFN-γ, IL-10 and CCL2, and diminished plasma concentrations of multiple variables as TNF-α, IL-6, IL-12, and CRP." (PMID 31233500, 2019).
acute abdomen (5 papers, 2018 to 2025). "In patients with acute abdomen, its combined use with CRP is proposed to identify low-risk patients." (PMID 36010070, 2022). "When significant values in the univariate regression analysis for acute abdomen and perforation were compared in the multivariate regression analysis, CRP, WBC, and FA levels were found to be prognostic." (PMID 31547519, 2019). "However, after the adjustment of the variables that are statistically significant in univariate analysis in the multivariate linear regression analysis with advanced stage method, FA, CRP, and WBC levels increased and remained associated with the risk of acute abdomen." (PMID 31547519, 2019). "Conventional inflammatory biomarkers, including leukocyte count (LC), neutrophil count (NC), and C-reactive protein (CRP), are routinely utilized to assist in diagnosing patients with suspected IAI and acute abdomen." (PMID 40067493, 2025).
Acute otitis media (5 papers, 2012 to 2022). Acute otitis media is a short and generally painful infection of the middle ear. "Instead, driving factors for a potential antibiotic overuse were a high CRP, the presence of acute otitis media, septic appearance and the length of oxygen therapy." (PMID 32807104, 2020).
adenomyosis (5 papers, 2021 to 2023). The growth of endometrial tissue inside the muscular wall of the uterine corpus. "In crude analysis, age, BMI ≥ 30, adenomyosis, WBC count, and CRP level at admission were significantly associated with prolonged hospitalization." (PMID 35978309, 2022).
adenopathy (5 papers, 2021 to 2024). "Other studies have also found other associated variables including presence of adenopathy and elevated CRP." (PMID 34069883, 2021). "His case evolved in a remitting/relapsing way with associated symptoms of fever, macular eruption, polyarthralgia, digital clubbing, adenopathy with a biological inflammatory state (elevated CRP and ESR)." (PMID 37048785, 2023). "Pertuzumab (1122) showed 128 reports of the neutrophil count decrease representing 11.4% of blood and lymphatic system disorder reactions, platelet count decrease of 69 (6.14%), lymphocyte count decrease of 19 (1.6%), and C reactive protein increase of 10 (0.89%)." (PMID 35222017, 2022).
alcoholic fatty liver disease (5 papers, 2009 to 2025). Lipid infiltration of the hepatic parenchymal cells that is due to alcohol abuse. "Inclusion of inflammation markers (e.g. C-reactive protein) and information on non-alcoholic fatty liver disease may have enabled us to categorise more precisely into metabolically healthy vs unhealthy." (PMID 34674643, 2021). "Additionally, alcoholic fatty liver disease markedly elevated serum immunoglobulins (immunoglobulin A and immunoglobulin E), activated T-lymphocytes, and increased C-reactive protein." (PMID 27799068, 2016). "Multivariate Logistic analysis displayed that SF, Hcy, CRP, and CAP were independent predictors of alcoholic fatty liver disease (p < 0.05)." (PMID 41480537, 2025).
alcoholic hepatitis (5 papers, 2011 to 2023). Acute hepatitis resulting from ingestion of alcohol. "A recent study indicated that cytokines such as tumor necrosis factor-alpha and interleukin-10 in adipose tissues of acute alcoholic hepatitis patients were elevated, and were correlated with the serum CRP concentration, implying that inflammation caused the production of CRP." (PMID 21806828, 2011). "In another reports, CRP levels were higher in patients with SIRS, infection, or alcoholic hepatitis and CRP was the most useful diagnostic marker of infection compared with other acute phase reactants such as the procalcitonin, lipopolysaccharide-binding protein, sCD14." (PMID 26498833, 2015). "Several reports proposed that serum C-reactive protein (CRP), tissue polypeptide-specific antigen (TPS), and interleukin-6 are noninvasive biomarkers of alcoholic hepatitis." (PMID 21806828, 2011).
ankylosis (5 papers, 2018 to 2023). Fixation and immobility of a joint. "For ankylosis, age, sex, HLA-B27, disease duration, CRP, and SPARCC were found significantly associated." (PMID 34386008, 2021). "Inflammation was assessed by C-reactive protein (CRP), and magnetic resonance imaging (MRI) of the sacroiliac joint using Spondyloarthritis Research Consortium of Canada score and a method of dichotomy to assess fat metaplasia, bone erosion, and ankylosis." (PMID 30572513, 2018). "In B27+ L+LM+ male patients, both L and LM levels (but not CRP) correlate with mSASS Scores: the correlation of LM levels is more robust than L levels, suggesting that both LM and L, to a lesser extent, reflect spinal inflammation and ankylosis progression." (PMID 35804445, 2022).
anorexia nervosa (5 papers, 2020 to 2025). A disorder most often seen in adolescent females characterized by a refusal to maintain a minimally normal body weight, an intense fear of gaining weight, a disturbance in body image, and, in postmenarcheal females, the development of amenorrhea. "Specifically, we found that higher levels of CRP were associated with lower odds of fasting with similar patterns observed when using anorexia nervosa as outcome (although, here, statistical evidence of an association was absent)." (PMID 32755646, 2020). "There were comparable associations between higher CRP and lower odds of anorexia nervosa (OR: 0.53, 95%CI: 0.24 to 1.22, p = 0.14) and bulimia nervosa (OR: 0.71, 95%CI: 0.43 to 1.17, p = 0.18)." (PMID 32755646, 2020). "It has recently been described that the level of CRP concentrations in infections of anorexia nervosa patients is limited." (PMID 40732135, 2025). "In univariable models, children in the middle and top third of IL-6 and CRP had greater odds of all diagnoses in adolescence, with the exception of anorexia nervosa in relation to CRP." (PMID 32755646, 2020). "Case-control studies suggest that women with anorexia nervosa may have lower levels of CRP, although no studies have investigated whether this association remains after weight restoration." (PMID 32755646, 2020).
aortic regurgitation (5 papers, 2010 to 2024). "Patients with aortic stenosis may have higher C-reactive protein levels than the levels in patients with aortic regurgitation." (PMID 21181071, 2010). "Model 6 included high ESR, high CRP, NIH criterion 1, NIH criterion 4, carotidynia, and aortic incompetence as independent variables; high ESR, NIH criterion 1, NIH criterion 4, and carotidynia remained as statistically significant in the final model." (PMID 35784279, 2022).